BRD4 (bromodomain containing 4)
Diseases named in the same sentence as BRD4 in open-access papers (continued):
Sharing a sentence is not in itself a finding about the gene and the disease.
colon cancer (continued). "Thus, in addition to BRD4 protein degradation, parallel cell death mechanisms are also responsible for A1874-induced anti-colon cancer cell activity." (PMID 32978368, 2020). "Interestingly, we also found that up‐regulated lncRNA POU6F2‐AS2 was found to inhibit the expression of miR‐377 and further up‐regulate the expression of BRD4 in colon cancer." (PMID 32100443, 2020). "Likewise, the promoter of the bromodomain protein, BRD4 is hypermethylated in 31%–50% of colon cancers, and AZA can be used to demethylate the promoter resulting in re-expression of BRD4 which impairs tumour growth." (PMID 25647662, 2015). "Notably, as PES1 is up-regulated by CD44, c-Jun, and BRD4 in liver or colon cancer cells." (PMID 31718704, 2019). "Inhibition of BRD4 decreased tumor growth and increased differentiation of CIMP+ colon cancer tumors." (PMID 36672877, 2023). "At the molecular level, A1874 is able to induce BRD4 protein degradation and the downregulation of BRD-dependent genes (c-Myc, Bcl-2 and cyclin D1) in colon cancer cells." (PMID 32978368, 2020). "The transfection of pBabe‐puro‐POU6F2‐AS2 increased the BRD4 expression, while miR‐377 mimics significantly decreased the expression of BDR4 in colon cancer cells." (PMID 32100443, 2020). "The BRD4-degrading PROTAC was able to induce caspase and apoptosis activation in colon cancer cells." (PMID 32978368, 2020). "First, A1874 was significantly more potent than other known BRD4/BET inhibitors (JQ1, CPI203, I-BET151) at inducing colon cancer cell apoptosis." (PMID 32978368, 2020). "Extending our prior immunoblotting work in cell-based assays, screening of SW48, CaCo2, HT29, LoVo and SW620 human colon cancer cell lines revealed moderate to high constitutive expression of ACE2, BRD2 and BRD4 proteins compared with CCD841 normal colonic epithelial cells." (PMID 36801948, 2023). "Furthermore, A1874-induced degradation of BRD4 protein and downregulated BRD-dependent genes (c-Myc, Bcl-2, and cyclin D1) in colon cancer cells." (PMID 32978368, 2020). "Although A1874-induced robust and potent BRD4 protein degradation, A1874-induced anti-colon cancer cell activity was not solely dependent on BRD4 degradation." (PMID 32978368, 2020). "In primary human colon cancer cells, pCan1 and pCan2, A1874 (100 nM) treatment led to robust degradation of BRD4 protein without affecting BRD4 mRNA expression." (PMID 32978368, 2020). "Furthermore, the BRD4-degrading PROTAC induced significant apoptosis activation in primary and established colon cancer cells." (PMID 32978368, 2020). "BRD2 may have both activation and inhibition functions, which was also confirmed by the bidirectional effect of JQ1, an inhibitor of the BRD4/BRD2 target, in colon cancer." (PMID 31523195, 2019). "A restrained migratory and invasive capability of colon cancer cells inhibited by MS417 reveals that BRD4 plays a critical role in metastasis, although this does not mean that BRD4 is the only protein that functions importantly in this progression." (PMID 25603177, 2015).
viral infection (26 papers, 2015 to 2025). "We show here that HSV-1 infection triggers BRD4 transition from chromosome association to transcriptional regulation for viral infection." (PMID 40812420, 2025). "Our study extends this understanding by highlighting BRD4’s role in parasitic infections such as schistosomiasis, which involve distinct immune regulatory mechanisms compared with bacterial or viral infections." (PMID 40616163, 2025). "BRD4 transitions to viral infection regulation by complexing with P-TEFb, a positive transcription elongation factor, and association with viral DNA." (PMID 40812420, 2025). "In respiratory diseases like Respiratory Syncytial Virus (RSV), BRD4 acts as a potent co-activator of ISGs during viral infections, initiating pro-inflammatory responses." (PMID 39066258, 2024). "BRD4 plays a pivotal role in regulating the response to viral infections by influencing transcriptional pathways that affect both innate and adaptive immunity." (PMID 39066258, 2024). "The dual functionality of BRD4, acting both as a promoter of viral replication and as a therapeutic target, highlights its potential in shaping the course of viral infections." (PMID 39066258, 2024). "In the intricate landscape of viral infection mechanisms, BRD4 emerges as a pivotal player with multifaceted roles." (PMID 39066258, 2024). "In recent years, BRD4 and BRD4 inhibitors have been extensively studied in the contexts of cancer, inflammation, viral infections, organ fibrosis, etc.." (PMID 39215370, 2024). "The BET family of proteins, particularly BRD4, has emerged as a pivotal regulator in both the innate immune response to viral infections and gene transcription modulation under these conditions." (PMID 39066258, 2024). "Inflammatory cells, IL-6, KC and BRD4 were synergistically induced in the lung of mice by viral infection and CS exposure, and the former three were decreased by JQ1 (BRD4 inhibitor) treatment." (PMID 36721187, 2023). "We found that the mRNA expression of BRD4 in the lung of mice was synergistically induced by viral infection and CS exposure." (PMID 36721187, 2023). "We also utilized murine and cellular models to investigate the roles of BRD4 in the enhanced inflammatory response during viral infection after CS exposure." (PMID 36721187, 2023). "Further, our intervention experiments show that the total leukocyte counts in BAL fluid and the expression of IL-6 and KC in the lung of mice are significantly decreased by BRD4 inhibitor JQ1 treatment during viral infection after CS exposure." (PMID 36721187, 2023). "Immunohistofluorescence indicates that BRD4 expression is significantly increased in the bronchial epithelial cells of the mouse lung after viral infection or CS exposure." (PMID 36721187, 2023). "More importantly, BRD4 expression in the lung of mice is synergistically induced during viral infection after CS exposure." (PMID 36721187, 2023). "Immunohistofluorescence staining showed that BRD4 was strongly expressed in the bronchial epithelial cells after CS exposure and/or viral infection." (PMID 36721187, 2023). "In this work, we further investigate BRD4’s role in alternative splicing in the context of airway viral infection using a highly selective BRD4-specific inhibitor, ZL0454." (PMID 37435059, 2023). "Mean fluorescence intensity analysis showed that BRD4 expression was synergistically induced by viral infection and CS exposure." (PMID 36721187, 2023). "During the process of viral infection, NF-κB RelA traffics to the nucleus and interacts with BRD4, CDK9 and other components of the positive transcription elongation factor (p-TEFb)." (PMID 33799525, 2021). "These interactions are consistent with the previous body of work, and demonstrate that viral infection reorders the interactome of BRD4, enriching it for transcription and splicing factors, as well as kinases, ATPases, and translational machinery." (PMID 33799525, 2021).
viral infection (continued). "It has been described that following RSV viral infection, the BRD4/RELA complex recruits the P-TEFb component CDK9 to IRF1 and IRF7 promoters for enhanced expression, and BRD4 inhibition has proven to alleviate viral-associated inflammation in this system." (PMID 34439792, 2021). "Then the CD8+ T cells response to antigen stimulation was investigated upon Brd4 deletion during viral infection." (PMID 34512660, 2021). "Several epigenes previously involved in response to viral infections stood out in our protein interaction analysis, such as BRD4, TOP2A, and TRIM28." (PMID 34031419, 2021). "Inhibitors of bromodomain protein 4 (BRD4), which receives much more attention in cancer than viral infection, was found to exhibit substantial anti-viral activity against PRV as well as a range of DNA and RNA viruses." (PMID 32208449, 2020). "Currently, accumulating studies have also revealed that the BRD2, BRD3 and BRD4 proteins participate in the host immune response against virus infection." (PMID 32962745, 2020). "Our data identify BRD4 inhibitors as a potent therapy not only for viral infection but also for cancer immunotherapy." (PMID 32208449, 2020). "Our findings provide molecular and structural bases to advance TP-based compounds toward the development of novel anti-cancer therapies and critical tools to characterize the role of BRD4 in viral infections, including SARS-CoV types." (PMID 32694708, 2020). "Our findings reveal a unique mechanism through which BRD4 inhibition restrains viral infection and points to its potent therapeutic value for viral infectious diseases." (PMID 32208449, 2020). "Because acetylation is critical in histone modification, we next sought to identify the mechanisms through which BRD4 inhibition suppresses viral infection." (PMID 32208449, 2020). "To determine how BRD4 inhibition influenced viral infection, we pre-treated PK15 cells with DMSO, JQ-1, OTX-015 and I-BET 151 for 24 h at 37°C." (PMID 32208449, 2020). "Mechanistically, the inhibitory effect of BRD4 inhibition on viral infection was mainly attributed to the attenuation of viral attachment." (PMID 32208449, 2020). "Previous studies have demonstrated that BRD4 facilitates viral infection through regulation of viral gene transcription." (PMID 32208449, 2020). "Thus, virus infection promotes JNK activation for release of BRD4 and its transition to transcription regulation." (PMID 40812420, 2025). "Additionally, our findings align with prior studies suggesting that BRD4 acts as a key regulator of immune pathways across various infectious and inflammatory diseases, including bacterial and viral infections." (PMID 40616163, 2025). "Furthermore, BRD4:Spliceosome interactions have been shown to be dynamic in the context of airway viral infection, and sensitive to bromodomain inhibition." (PMID 37435059, 2023). "In addition, BRD2 and BRD3 regulate the expression of the viral entry receptor angiotensin-converting enzyme 2 (ACE2) to facilitate the de novo viral infection of SARS-CoV-2 while BRD4 is the least effective in this task." (PMID 37686037, 2023). "This suggests that modulation of similar or same target proteins (e.g., BET protein family) or pathways by different regulatory agents (different BET/BRD4 inhibitors) may induce distinct functional outcomes in different viral infections." (PMID 35758684, 2022). "As Brd4 inhibition with small molecules has attracted great attention in cancer and viral infection therapies, we then evaluated whether Brd4 inhibition represses the CD8+ T-cell response to viral infection." (PMID 34512660, 2021). "Moreover, targeting Brd4 with inhibitors severely impairs CD8+ T cell function during viral infection." (PMID 34512660, 2021). "BRD4 inhibition also de-compacted chromatin structure and induced the DNA damage response, thereby triggering the activation of cGAS-mediated innate immunity and increasing host resistance to viral infection both in vitro and in vivo." (PMID 32208449, 2020).
viral infection (continued). "Given that BRD4 participates in gene transcription, we assessed whether BRD4 inhibition might perturb viral gene transcription and impair viral infection." (PMID 32208449, 2020). "BRD4 has been shown to regulate virus infection with diverse mechanisms." (PMID 30068949, 2018). "BRD4 plays a diverse role in modulating viral infection by RNA and DNA viruses." (PMID 27764245, 2016). "Whether TLR ligands enhance the interaction of BRD4 with the Ifnb promoter by activating these or other HATs and/or by inhibiting HDACs is unknown, but viral infection has been reported to induce the localized hyperacetylation of histones at the Ifnb promoter." (PMID 25891802, 2015). "Thus, stress signals from virus infection could induce BRD4 transition from host gene regulation to viral gene transcription and infection." (PMID 40812420, 2025). "Thus, further studies are needed to characterize BRD4 modifications in viral infection." (PMID 40812420, 2025). "BRD4, the most studied member of this family, binds to acetylated lysines on both histones and non-histone proteins, thereby regulating gene expression and influencing diverse cellular functions such as the cell cycle, tumorigenesis, and immune responses to viral infections." (PMID 39066258, 2024). "Papillomavirus E6 and E7 proteins were suggested to enable viral genome replication, Brd4 can enhance replication by concentrating viral processes in specific regions of the host nucleus, and the contribution of Sp100 in regulating the viral infection can be further investigated." (PMID 37376685, 2023). "Upon viral infection, IRF1 are induced, complexes with BRD4 and both factors load pSer2 Pol II onto target gene promoters." (PMID 38601157, 2024). "Recent work indicates that BRD4 plays a considerable role in differentiation and maintenance of terminal effector CD8+ T cells during viral infection through tight control of terminal effector–specific super-enhancers." (PMID 38775157, 2024). "Acetylated protein interactions enable dynamic reconfiguration of the BRD4 CRC in response to extracellular signals, differentiation states and viral infections." (PMID 38601157, 2024). "In viral infection, the vaccinia virus protein F14 was recently shown to selectively inhibit a subset of NF-κB signaling induced by TNF-α, i.e., suppressing BRD4 recruitment to the promoters of CCL2 and CXCL10." (PMID 37686037, 2023). "All designed compounds exhibited effects against BRD4 and HDAC class I, mainly HDAC-1 and -2, being promising prototypes to be evaluated against viral infections by acting through epigenetic mechanisms." (PMID 34959707, 2021). "In this context, the design of hybrid compounds acting through dual bromodomain (BRD4) and HDAC class I inhibitors seems to be a promising approach for several viral infections." (PMID 34959707, 2021). "To determine the role of Brd4 in regulation of CD8+ T cells response to viral infection, we next established an acute viral infection mouse model to examine the differentiation and function of CD8+ T cells upon Brd4 deletion." (PMID 34512660, 2021). "Together, these findings demonstrate that Brd4 is required for effector CD8+ T-cell clonal expansion and terminal differentiation during viral infection." (PMID 34512660, 2021). "The family II extra-terminal bromodomains (BET) (BRD2, BRD3, BRD4, and BRDT) are also involved in several viral infections since the replication and transcriptional viral regulation depends on BRD recognition." (PMID 34959707, 2021). "BRD4 was positively correlated with the expression of IL-6 and interleukin-8 (IL-8) in bronchial epithelial cells (BEAS-2B cells) following exposure to cigarette smoke and viral infection." (PMID 39215370, 2024). "To date, there have been no reports with respect to the effects of above three BET/BRD4 inhibitors on viral infection." (PMID 35758684, 2022).
viral infection (continued). "Among these proteins, BRD4 recognizes acetylated histones via its two bromodomains (BD1 and BD2) and recruits transcription factors, thereby playing a pivotal role in transcriptional regulation and chromatin remodeling during viral infection." (PMID 35758684, 2022). "Furthermore, targeting Brd4 with JQ1, a pan-BRD inhibitor, impeded CD8+ T-cell clonal expansion and effector differentiation during acute viral infection." (PMID 34512660, 2021). "Interestingly, inhibition of BRD4 with JQ1 results in impaired proliferation of Tax-positive HTLV-1-infected cells, and then, in reduced Tax-mediated cell transformation and tumorigenesis, suggesting that BET inhibitors could also be used as anti-cancer therapy in tumors caused by viral infections." (PMID 34439792, 2021). "Chiefly, Brd4 regulates CDK9 and RNAP II phosphorylation during viral infection." (PMID 27764245, 2016). "Because BRD4 has emerged as a protein target for the SARS-CoV-2 virus envelope protein E6, the TP-based inhibitors, and particularly the most potent compound SRX3212, could provide critical tools in determining the role of BRD4 in viral infections, including SARS-CoV types." (PMID 32694708, 2020). "However, HPV31 genomes that encode an E2 protein defective for BRD4 binding are maintained in stable cell lines, suggesting either that BRD4 is not essential for genome maintenance of all HPV strains, or that the interaction of BRD4 and E2 is more complex in the background of a viral infection." (PMID 26008695, 2015).